OPRM1 (opioid receptor mu 1)
Diseases named in the same sentence as OPRM1 in open-access papers (continued):
Sharing a sentence is not in itself a finding about the gene and the disease.
nicotine dependence (15 papers, 2006 to 2022). Physical and psychological dependence on nicotine. "In consideration of the significance of μ-opioid receptor systems in physiological mechanisms about the reward center, biologically, it is plausible that OPRM1 polymorphisms can modulate the risks of nicotine-dependence." (PMID 29137427, 2017). "Present studies of the possible association of nicotine dependence and OPRM1-A118G polymorphism evince mixed findings." (PMID 29137427, 2017). "Genome-wide association researches also showed that the OPRM1 gene is closely related to nicotine dependence." (PMID 29137427, 2017). "Given this, we pooled several databases to analyze the associations between nicotine-dependence and the OPRM1-A118G polymorphism." (PMID 29137427, 2017). "Mainstream clinical A118G OPRM1 polymorphism analysis focuses on opioid-induced analgesia and opioids, vulnerability to alcohol and nicotine addiction, and therapy response." (PMID 25618602, 2015). "The OPRM1 gene encodes the mu-opioid receptor, which has been associated with drug addiction, including nicotine dependence." (PMID 25161819, 2014). "As suspected in the case of alcohol, genetic variations of OPRM1 might impact the risk of developing nicotine dependence." (PMID 29137427, 2017). "The studies evaluated the associations between OPRM1 A118G polymorphism and nicotine dependence." (PMID 29137427, 2017). "Whether opioid-receptor mu 1 (OPRM1) A118G polymorphism (rs1799971) is associated with nicotine dependence is controversial." (PMID 29137427, 2017). "They concluded that subjects with the OPRM1 AA allele had higher risk for nicotine dependence." (PMID 25598501, 2015). "In rodent studies, there was evidence that OPRM1 G allele might play a role in susceptibility to nicotine addiction." (PMID 24447405, 2014). "To investigate whether OPRM1 contributes to the susceptibility of smoking initiation and nicotine dependence, we genotyped 11 SNPs in the gene for 688 Caucasian subjects of lifetime smokers and nonsmokers." (PMID 16887046, 2006). "The μ-opioid receptor (OPRM1) plays an important role in nicotine dependence because of its ability to bind β-endorphins and enkephalins, which are released after nicotine ingestion." (PMID 30973902, 2019). "It has been proposed that vulnerability to nicotine addiction is moderated byvariation at the μ-opioid receptor locus (OPRM1), but results from human studiesvary and prospective studies based on genotype are lacking." (PMID 27459726, 2016). "In combination with NRT patch, participants were informed that their doses of oral NRT were based either on their mu-opioid receptor (OPRM1) genotype, or their nicotine dependence questionnaire score (phenotype)." (PMID 22509402, 2012). "Currently, no studies aimed at examining the relationship between DRD2, DRD3, COMT, and OPRM1 polymorphisms, the 5-HTTLPR genotype, and smoking habit and nicotine addiction in patients with treatment-resistant mood disorders and schizophrenia-spectrum disorders." (PMID 35455685, 2022). "With regard to the potential mechanisms, we speculated that nicotine dependence induced by OPRM1 might partially account for this." (PMID 32194810, 2020). "The evidence from animal experiments, treatment response and linkage study suggests that OPRM1 may be a gene contributing to the liability of tobacco smoking and nicotine dependence." (PMID 16887046, 2006). "Interestingly, the OPRM1 gene is located at 6q24-25, about 4 million basepairs from a suggestive linkage peak of nicotine dependence." (PMID 16887046, 2006). "We hypothesized that the ANKK1-DRD2 rs1800497, DRD3 rs6280, COMT rs4633, and OPRM1 rs1799971 polymorphisms, together with the 5-HTTLPR genotype, could be involved in the smoking habits and nicotine dependence in patients with treatment-resistant psychiatric disorders." (PMID 35455685, 2022). "Additionally, the OPRM1 gene is located in a region showing linkage to nicotine dependence." (PMID 16887046, 2006).
nicotine dependence (continued). "Only one of the reviewed studies looked at craving as an aspect of nicotine dependence specifically, and it found no relation between OPRM1 A118G and craving." (PMID 26449981, 2015).
fibromyalgia (14 papers, 2017 to 2026). A chronic disorder of unknown etiology characterized by pain, stiffness, and tenderness in the muscles of neck, shoulders, back, hips, arms, and legs. "We also confirmed that rs1799971 SNP (OPRM1 gene) seem to confer higher susceptibility to fibromyalgia." (PMID 29486785, 2018). "We also confirmed that the rs1799971 SNP (OPRM1 gene) seems to confer genetic risk of fibromyalgia." (PMID 29486785, 2018). "Guanosine triphosphate cyclohydrolase 1 (GCH1) and opioid receptor μ1 (OPRM1) are candidate neurotransmitter-related genes that may confer fibromyalgia susceptibility." (PMID 29486785, 2018). "However, whether GCH1 and OPRM1 genes are associated with fibromyalgia susceptibility in the Caucasian population is unknown." (PMID 29486785, 2018). "Genotype frequencies of the polymorphisms rs1799971 (OPRM1), rs6296 (5-HT1A) and the triallelic 5-HTT for the whole group, as well as fibromyalgia (FM) patients and healthy controls (HC) separately." (PMID 36342939, 2022). "Genotype frequencies of the polymorphisms rs1799971 (OPRM1), rs6296 (5-HT1a), and the triallelic 5-HTT for 130 fibromyalgia (FM) patients and 134 healthy controls (HC)." (PMID 28282362, 2017).
neuropathy (11 papers, 2012 to 2023). A disorder affecting the nervous system that manifests with pain, tingling, numbness, and/or muscle weakness. "We analyzed genes known to be targeted by cannabigerol and other cannabinoids, including Cnr1, Cnr2, Gpr55, Faah, Mgll, Adra2a-c, Pparg, or to have been previously published as volatile in a cisplatin-induced neuropathy setting in DRG, including Drd2, Gfap, and Oprm1." (PMID 37895913, 2023).
schizophrenia (11 papers, 2012 to 2022). A major psychotic disorder characterized by abnormalities in the perception or expression of reality. "Due to these properties, OPRM1 has been reported associated with the progression of Alzheimer's disease, Parkinson's disease, Schizophrenia and so on 28-30." (PMID 32194810, 2020). "The present study demonstrated for the first time that the OPRM1 polymorphism may be a risk factor for schizophrenia in the Han Chinese." (PMID 23560613, 2013). "Regarding OPRM1, a study stipulated that the studied polymorphism can influence the myelination of axons especially in cortical neurons, which may play a role in the pathogenesis of schizophrenia." (PMID 31557839, 2019).
alcohol use disorder (10 papers, 2013 to 2025). "There is optimism about potential pharmacogenetic applications for the treatment of alcohol use disorders, with particular interest in the OPRM1 A118G polymorphism as a moderator of naltrexone response." (PMID 25217046, 2014). "The role of OPRM1 A118G (Asn40Asp) polymorphism in susceptibility to alcohol use disorders and alcohol consumption has remained controversial in prior research." (PMID 23729673, 2013). "In the current study, we set out to analyze the possible association with the OPRM1 A118G (Asn40Asp) polymorphism and both alcohol use disorders and alcohol consumption in three separate large general population-based cohorts of Finnish origin." (PMID 23729673, 2013). "Therefore, while the association of OPRM1 with alcohol use disorder etiology remains controversial, findings suggest the relevance of OPRM1 for a phenotype of clinical interest: reduction in alcohol consumption during treatment with naltrexone versus placebo." (PMID 25217046, 2014). "OPRM1 is a primary candidate gene that has been examined in association with OUD and other addictive behaviors such as alcohol use disorder, with both genetic and epigenetic associations identified." (PMID 33763662, 2020).
colorectal cancer (10 papers, 2022 to 2025). A primary or metastatic malignant neoplasm that affects the colon or rectum. "Background/Objectives: Pain management in colorectal cancer is influenced by genetic variability in opioid receptor genes (OPRM1 and OPRD1), potentially affecting opioid efficacy and adverse drug reactions (ADRs)." (PMID 40006034, 2025). "This study evaluated the association of OPRM1 (rs1799971 and rs510769) and OPRD1 (rs2236861) polymorphisms with pain severity, opioid efficacy, and ADRs in Chilean colorectal cancer patients." (PMID 40006034, 2025). "This study explored the genetic variability in opioid receptor genes (OPRM1 and OPRD1) and their association with pain and adverse drug reactions (ADRs) in colorectal cancer patients in a Latin American Mestizo sample (Chileans)." (PMID 40006034, 2025). "This study was conducted to examine the association between the A118G polymorphism of the OPRM1 gene and the risk of increased VAS scores in patients with colorectal cancer who underwent laparoscopic radical resection for which fentanyl was used." (PMID 37217861, 2023). "Based on this background, this study hypothesizes that polymorphisms in OPRM1 and OPRD1 influence the response to opioids, thereby conditioning their therapeutic effectiveness and toxicity in patients with advanced-stage colorectal cancer." (PMID 40006034, 2025).
diabetes (9 papers, 2016 to 2025). "As the expression of Oprm1 gene (MOR protein-coding gene) remained unchanged in the lumbar DRG during diabetes, we hypothesized that the loss of MOR was due to its degradation." (PMID 33462216, 2021). "The amount of available data on the association between diabetes and polymorphisms in the “pain genes” (COMT and OPRM1) is very limited." (PMID 40649008, 2025). "In conclusion, both diabetes and genetic polymorphisms in the COMT and OPRM1 genes play an important role in postoperative opioid demand and pain perception." (PMID 40649008, 2025). "The aim of the present study was to investigate a possible association of the COMT and OPRM1 genotypes with pain perception in patients undergoing total hip replacement (THR) and total knee replacement (TKR), taking into account aspects such as age, sex and diabetes." (PMID 36292660, 2022). "The aim of the study was to investigate a possible association of the catechol-O-methyltransferase (COMT) and μ-opioid receptor (OPRM1) genotypes with pain perception in patients undergoing total hip replacement and total knee replacement taking into account aspects such as age, sex and diabetes." (PMID 36292660, 2022). "Furthermore, factors such as sex, age and diagnosed or (treated) diabetes did not influence the differences in the pain threshold and pain tolerance in patients with different variants of the COMT and OPRM1 genes." (PMID 36292660, 2022).
bone cancer (8 papers, 2014 to 2024). A primary or metastatic malignant neoplasm affecting the bone or articular cartilage. "In a rat model of bone cancer pain, tumor cell inoculation resulted in the downregulation of OPRM1, which correlated with increased HDAC expression." (PMID 37670983, 2023).
autism (7 papers, 2014 to 2024). Persistent deficits in social interaction and communication and interaction as well as a markedly restricted repertoire of activity and interest as well as repetitive patterns of behavior. "Here we back-translated applied behavior analysis (ABA)-based behavioral interventions to mice lacking the MOR (Oprm1−/−), as a model of autism with blunted reward processing." (PMID 30242222, 2018). "Mice lacking a functional MOR gene (Oprm1−/− mice) display abnormal social behavior and major autistic-like core symptoms, making them an animal model of autism." (PMID 25225634, 2014).
drug dependence (6 papers, 2008 to 2021). "In addition, several studies have reported evidence of an association between OPRM1 and drug dependence." (PMID 23584813, 2008). "In the present study, we further analyzed the interactive effect of OPRM1, OPRD1, and OPRK1 variants on alcohol or drug dependence using a pattern discovery-based method." (PMID 24533225, 2013). "Considering the close biological interaction of the three receptors, we hypothesized that variation in their genes (OPRM1, OPRD1, and OPRK1) might have joint effects on risk for alcohol or drug dependence." (PMID 24533225, 2013).
peripheral nerve injury (6 papers, 2014 to 2022). Injury to a peripheral nerve. "Dnmt3a, an epigenetic repressor, participates in epigenetic silencing of several genes (such as Oprk1 and Kcna2 besides Oprm1) in the injured DRG following peripheral nerve injury." (PMID 29170626, 2017).
binge eating disorder (5 papers, 2013 to 2024). Recurrent episodes of over-eating. "Although the effects are less clear in humans, there is some genetic evidence that implicates the gain of function 118G polymorphism of OPRM1, the MOR gene, in binge eating disorder." (PMID 23245760, 2013).
diabetic neuropathy (5 papers, 2016 to 2025). A chronic, pathological complication associated with diabetes mellitus, where nerve damages are incurred due to diabetic microvascular injury involving small blood vessels that supply these nerves, resulting in peripheral and/or autonomic nerve dysfunction. "The gene-burden analysis of rare variants in our 45 target pain genes revealed significant associations with neuropathic pain in diabetic neuropathy for 2 genes: OPRM1 and SCN9A." (PMID 39471050, 2025).
migraine (5 papers, 2012 to 2025). "This study investigated if the OPRM1 gene, A118G SNP was associated with migraine head pain severity in females." (PMID 22752568, 2012). "Logistic regression analysis adjusting for age effects showed the A118G SNP of the OPRM1 gene to be significantly associated with migraine pain severity in the test population (P = 0.0037)." (PMID 22752568, 2012). "Secondly because, this is the first study associating the OPRM1 gene with migraine pain severity, replication in additional, larger populations is necessary to enhance confidence in results." (PMID 22752568, 2012). "This is the first study to investigate the association between the OPRM1 A118G SNP and migraine head pain severity." (PMID 22752568, 2012). "In conclusion the results from this study suggest that the A118G genotypes of the OPRM1 gene may influence migraine-associated head pain in females." (PMID 22752568, 2012). "As such, this study has taken the first step towards investigating the association between the A118G SNP in the OPRM1 gene and migraine pain severity and has provided initial evidence that the presence of the G118 allele may increase the severity of migraine pain." (PMID 22752568, 2012). "However, the A118G SNP is only one of the more than 100 known SNPs in the OPRM1 gene and therefore further studies are required to investigate other candidate, albeit rare SNPs to understand their influence on pain associated with migraine." (PMID 22752568, 2012). "The groundwork for future investigations, suggests Asarinin as a promising candidate for migraine management by targeting OPRM1 pathway." (PMID 39215033, 2024). "Asarinin holds promise as a therapeutic agent, offering a multifaceted approach to addressing the intricate landscape of migraine management by targeting OPRM1." (PMID 39215033, 2024). "By directing Asarinin toward OPRM1, it has the potential to inhibit OPRM1, further reducing the synthesis of CGRP and the activation of pain stimulation from other biomarkers implicated in migraine attacks." (PMID 39215033, 2024). "OPRM1 emerges as a pivotal hub, instigating the activation of GNAS and GNB1, subsequently influencing proteins such as RAMP1, RAMP2, RAMP3, CALCB, CALCR, and SLC5A2 all implicated in migraine attacks." (PMID 39215033, 2024). "Second, other pain-related genetic polymorphisms, such as BDNF rs2049046 and G-712A reported in migraine studies or OPRM1 A118G reported in PDM study, might also be potential candidates of genetic modulators of chronic pain-sculpted brain complexity." (PMID 30524221, 2018). "Hence the current study focused only on the A118G SNP in the OPRM1 gene as a prime candidate in investigating migraine pain." (PMID 22752568, 2012). "The network analysis suggested that the specific proteins such as OPRM1, GNB1, and GNAS are interlinked and interacted with the migraine with aura pathological targets like RAMP154, RAMP255, RAMP356, CALCR57, CALCB58, ADM59, IAPP60, and SLC5A261." (PMID 39215033, 2024).
pancreatic cancer (5 papers, 2019 to 2024). "OPRM1 and GNG7 were reported to be associated with oesophageal cancer and pancreatic cancer, respectively." (PMID 31640538, 2019).
COVID-19 (4 papers, 2022 to 2025). A disease caused by infection with severe acute respiratory syndrome coronavirus 2. "The primary aim of this study was to investigate the possible associations between selected SNPs of OPRM1 (rs1799971), COMT (rs4680), BDNF (rs6265), and HTR1B (rs6296) and the presence of de novo long-term post-COVID pain in previously hospitalized COVID-19 survivors." (PMID 35893072, 2022). "This exploratory study showed that four polymorphisms associated with pain experience (SNPs of OPRM1 (rs1799971), COMT (rs4680), BDNF (rs6265), and HTR1B (rs6296)), did not appear to predispose for developing post-COVID pain in previously hospitalized COVID-19 survivors." (PMID 35893072, 2022). "The current study did not reveal significant differences in the presence of OPRM1 (rs1799971), COMT (rs4680), BDNF (rs6265), and HTR1B (rs6296) SNPs between previously hospitalized COVID-19 survivors with and without post-COVID pain." (PMID 35893072, 2022).
eating disorder (4 papers, 2009 to 2025). A broad group of psychological disorders with abnormal eating behaviors leading to physiological effects from overeating or insufficient food intake. "Finally, beyond addiction, the role of the Oprm1 and Oprd1 genes in impulsivity has implications for understanding and treating attention deficit hyperactivity disorder, eating disorders, gambling and other disorders of impulse control." (PMID 19198656, 2009).
Nausea (4 papers, 2013 to 2024). A sensation of unease in the stomach together with an urge to vomit. "These functions of the NDG, in concert with its remarkable level of Oprm1 expression may serve to partially explain opioid-induced nausea, especially given the prominent role of the nodose in nutrient sensing and emesis." (PMID 33424545, 2020).
osteoarthritis (4 papers, 2020 to 2025). A noninflammatory degenerative joint disease occurring chiefly in older persons, characterized by degeneration of the articular cartilage, hypertrophy of bone at the margins and changes in the synovial membrane. "Building on this knowledge, the present study investigates how polymorphisms in the OPRM1 and COMT genes are associated with analgesic requirements in diabetic and non-diabetic patients with osteoarthritis (OA) following total hip or knee arthroplasty." (PMID 40649008, 2025).